TNF (tumor necrosis factor)
Diseases named in the same sentence as TNF in open-access papers (continued):
Sharing a sentence is not in itself a finding about the gene and the disease.
rheumatoid arthritis (continued). "Present data regarding TNF-α SNP association with periodontitis are in accordance with other case-controls investigations and support a role for TNF-α in chronic inflammation and bone remodeling, as shown for different diseases such as rheumatoid arthritis." (PMID 24274085, 2013). "It is important to note that in the VA patient population studied, anti- TNF drugs were prescribed less than 20 percent of the time, while in the general population as many as 40 percent of rheumatoid arthritis patients receive anti-TNF drug treatment." (PMID 24498926, 2013). "TNFα blockers have drastically improved rheumatoid arthritis prognosis by preventing joint destruction in DMARD resistant patients." (PMID 24373564, 2013). "Adalimumab, a tumor necrosis factor (TNF) inhibitor is used in patients with e.g. rheumatoid arthritis and several autoimmune disorders." (PMID 24244376, 2013). "Tumor necrosis factor alpha (TNFα) blockers have drastically improved the prognosis of rheumatoid arthritis by preventing joint destruction in DMARD resistant patients." (PMID 24373564, 2013). "TNF-α is thought to play a crucial role in rheumatoid arthritis since it enhances the production of inflammatory disease-related molecules such as IL-1 or IL-6 in the serum and synovial fluid." (PMID 23762085, 2013). "Tumor necrosis factor alpha (TNF-α) is a proinflammatory cytokine produced in many inflammatory and autoimmune diseases such as rheumatoid arthritis, Crohn's disease, multiple sclerosis, or chronic hepatitis C." (PMID 23533448, 2013). "In rheumatoid arthritis and other systemic inflammatory diseases several TNF-α inhibitors have been used (adalimunab [humira], etanercept [enbrel], infliximab [remicade])." (PMID 23587252, 2013). "We present the case of a 40-year-old man with severe rheumatoid arthritis being treated with high-dose anti-tumor necrosis factor α therapy (adalimumab), who developed simultaneous lymphoma and breast cancer with lymph node metastases." (PMID 23320919, 2013). "There are no genetic predictors of response to one of the most widely used classes of drugs in the treatment of rheumatoid arthritis—biological modifiers of the inflammatory cytokine tumor necrosis factor-alpha (or anti-TNF therapy)." (PMID 23555300, 2013). "Recently, it was reported that PGRN directly binds to TNF receptors and suppresses TNF-α-mediated inflammation in a mouse model of rheumatoid arthritis." (PMID 23972823, 2013). "Certolizumab pegol (Cp) is one of the anti-TNF-α agents introduced for the management of CD and rheumatoid arthritis." (PMID 24578833, 2013). "Tumor necrosis factor-alpha antagonism is an important treatment strategy in patients with rheumatoid arthritis, psoriatic arthritis, vasculitis, and ankylosing spondylitis." (PMID 23970991, 2013). "As millions of people are treated with TNF blocking agents to treat inflammatory diseases such as rheumatoid arthritis and Crohn’s disease, it is critical to understand the precise role of TNF in response to infection." (PMID 23874808, 2013). "To date, only two studies have been published that correlate the clinical response and immunogenicity to anti-TNF drugs in rheumatoid arthritis (RA) patients who switched to a second anti-TNF drug." (PMID 23890223, 2013). "In fact, transgenic overexpression of TNFα in mice leads to a robust inflammatory state characterized by bone and joint destruction that closely mimics that of human rheumatoid arthritis." (PMID 24278766, 2013). "Studies have shown the importance of CD4+ T cells, B cells, and cytokines such as RNAKL, TNFα, IL-1, and IL-17 in the pathogenesis of rheumatoid arthritis." (PMID 24222748, 2013). "In rheumatoid arthritis activated T and B cells are potent inducers of osteoclastic bone resorption through direct RANKL secretion as well as through production of TNFα, a cytokine of key importance in the etiology of rheumatoid arthritis." (PMID 24278766, 2013).
rheumatoid arthritis (continued). "In the pathogenesis of rheumatoid arthritis, various inflammatory mediators are found to be involved, among which tumour necrosis factor (TNF) α is the main agent." (PMID 23970975, 2013). "TNF-α signaling has been successfully targeted by anti-TNF antibodies (e.g. Etanercept) in the case of rheumatoid arthritis." (PMID 23468959, 2013). "In rheumatoid arthritis the administration of recombinant IL-1RA is clinically effective in dampening local inflammation although clinical efficacy is less than seen for TNF blocking agents." (PMID 23991111, 2013). "Etanercept is a monoclonal antibody targeted against Tumour Necrosis Factor-alpha (TNF-a) which is an effective treatment for rheumatoid arthritis and is in cases where conventional disease modifying agents such as methotrexate have failed." (PMID 23573450, 2013). "In major illnesses, such as rheumatoid arthritis and certain cancers, the expression of TNF is elevated." (PMID 24199619, 2013). "Increased risk for non-melanoma skin cancer is associated with thiopurine treatment in IBD, with the combination of anti-TNF and methotrexate in rheumatoid arthritis and with PUVA, cyclosporine and anti-TNF treatment in psoriasis." (PMID 23987103, 2013). "The therapeutic strategy against rheumatoid arthritis (RA) has been considerably improved by clinical application of biological agents, including tumor necrosis factor (TNF) inhibitors." (PMID 24286472, 2013). "Adalimumab, a TNF-α antagonist, has shown remarkable efficacy in rheumatoid arthritis, ankylosing spondylitis, psoriatic arthritis, Crohn's disease, and plaque-type psoriasis." (PMID 24489444, 2013). "Recently, TNF-α blockers were suggested for the treatment of inflammatory disorders including rheumatoid arthritis, psoriasis and psoriatic arthritis." (PMID 23286283, 2013). "Anti-cytokine strategies, such as application of anti-TNF-α antibodies, have been proven to be effective in autoimmune disorders, such as rheumatoid arthritis or inflammatory bowel disease." (PMID 22094132, 2012). "A large UK prospective study compared the rates of MTB amongst the three approved TNF-α inhibitors, using data from a large registry of biological treatments used in patients with rheumatoid arthritis." (PMID 23304607, 2012). "In many European countries, restrictions exist around the prescription of anti-tumor necrosis factor (anti-TNF) treatments for rheumatoid arthritis (RA)." (PMID 23039402, 2012). "The CD4+ and CD8+ T cells expressing CX3CR1 predominantly produce IFN-γ and TNF-α, and these T cells infiltrate the synovium in patients with rheumatoid arthritis." (PMID 22235377, 2012). "Infliximab, a chimeric (human-mouse) monoclonal antibody to human tumour necrosis factor-α (TNF-α), has proved to be effective in the treatment of rheumatoid arthritis (RA) in several pivotal randomised controlled trials." (PMID 23006627, 2012). "Those agents include "Etanercept" (a fusion protein that neutralizes soluble TNF-α in psoriasis, rheumatoid arthritis, and psoriatic arthritis) and "Enfuvirtide" (a synthetic peptide that acts extracellularly and inhibits HIV entry into T cells)." (PMID 23259659, 2012). "TNFα antagonists have been found to be efficacious in the treatment of many immune mediated inflammatory diseases, including rheumatoid arthritis, polyarticular juvenile rheumatoid arthritis, Crohn's disease, psoriatic arthritis, and ankylosing spondylitis." (PMID 22271346, 2012). "The use of anti-TNF treatments has provided new insights into the treatment of inflammatory rheumatic diseases, particularly AS and rheumatoid arthritis (RA)." (PMID 23025387, 2012). "Several TNF-blocking drugs have been developed and approved, and are in clinical use for inflammatory diseases such as rheumatoid arthritis, psoriasis and ankylosing spondylitis." (PMID 22737386, 2012). "There have been numerous TNF antibody preparations which have proven beneficial in the treatment of rheumatoid arthritis." (PMID 22348221, 2012).
rheumatoid arthritis (continued). "Human studies demonstrate that patients receiving TNF-α inhibitors for chronic inflammatory diseases (rheumatoid arthritis, Crohn disease) can develop reactivation TB disease." (PMID 22761866, 2012). "The cytokine TNF-α plays a key role in the skeletal muscle wasting present in chronic diseases, such as cancer, sepsis, and rheumatoid arthritis, conditions in which a raise in the plasma TNF-α concentration have been described." (PMID 22536489, 2012). "We report a severe case of right upper lobe pneumonia caused by L. pneumophila serotype 1, mimicking M. tuberculosis reactivation, in a patient receiving the TNF-α antagonist adalimumab for rheumatoid arthritis." (PMID 23092579, 2012). "To date, measures that target TNFα activities are already used in the clinic, primarily in inflammatory diseases such as rheumatoid arthritis, motivating researchers to determine their impact on malignant diseases." (PMID 24213226, 2012). "In several rheumatic diseases (e.g. rheumatoid arthritis, ankylosing spondylitis), TNF-α concentration is elevated in affected joints, which seems to play a prominent role in joint destruction." (PMID 22737386, 2012). "We report a female patient with rheumatoid arthritis which was refractory to methotrexate, leflunomide, and anti-TNF therapy." (PMID 23304614, 2012). "In human rheumatoid arthritis fibroblast-like synoviocytes, artesunate, an artemisinin derivative, has the ability to inhibit TNF-α- induced production of proinflammatory cytokines via inhibition of NF-κB and PI3 kinase/Akt signal pathway." (PMID 22514713, 2012). "TNF plays a key role in the pathogenesis of rheumatoid arthritis (RA) and other auto-immune diseases." (PMID 23217265, 2012). "Tocilizumab (TCZ), an anti-interleukin-6 therapy, is approved for the treatment of moderate to severe rheumatoid arthritis including patients with anti-TNFα-therapy failure." (PMID 23304614, 2012). "Synovial fibroblasts (SFB; purity > 98%) were obtained from rheumatoid arthritis (RA) and osteoarthritis (OA) patients (n = 6 each) and stimulated with TNF-α or TGF-β1 for 0, 1, 2, 4, or 12 hours." (PMID 22682473, 2012). "Using a case study in rheumatoid arthritis a Bayesian mixed treatment comparison model is fit to estimate the relative efficacy of five anti-TNF agents currently licensed in Europe." (PMID 23130635, 2012). "Similar to rheumatoid arthritis (RA), several trials in PsA have shown excellent clinical results with anti-TNFα agents such as etanercept, infliximab, and adalimumab." (PMID 22649467, 2012). "The introduction of anti–tumor necrosis factor (anti-TNF) biologic drugs in the clinical management of rheumatoid arthritis (RA) has proven highly successful in suppressing both inflammation and joint damage in many of the treated patients." (PMID 21952740, 2012). "TNF-α is a crucial proinflammatory cytokine in many inflammatory disorders including rheumatoid arthritis, ankylosing spondylitis, psoriasis/psoriatic arthropathy, or inflammatory bowel diseases." (PMID 23060289, 2012). "Tumor necrosis factor (TNF)-α is a multifunctional, proinflammatory cytokine which plays an important role in several autoimmune diseases like rheumatoid arthritis, pernicious anemia, diabetes mellitus etc." (PMID 23284977, 2012). "Gold salts has previously been used in the treatment of rheumatoid arthritis but have been replaced by biologicals such as TNF-α inhibitors." (PMID 23140489, 2012). "Fifty-two patients with active rheumatoid arthritis despite therapy with TNF-inhibitors were included in the national rituximab registry." (PMID 22770118, 2012). "The upregulation of TNF-α gene expression has been involved in the pathogenesis of several autoimmune inflammatory illnesses, such as systemic lupus, rheumatoid arthritis, and inflammatory bowel disease." (PMID 23133455, 2012).
rheumatoid arthritis (continued). "The production of proinflammatory cytokines, e.g., TNF-α, IL-1β and IL-6, is a key factor in chronic inflammatory diseases, such as rheumatoid arthritis, Crohn’s disease, psoriasis and asthma." (PMID 23056531, 2012). "This is also highlighted by the enhanced incidence of TB reactivation during treatment with biologicals targeting TNF, which are used in treating inflammatory disorders such as rheumatoid arthritis, Crohn's disease, and psoriasis." (PMID 22589713, 2012). "Anti-tumor necrosis factor (TNF) therapy is considered the global standard in the treatment of rheumatoid arthritis (RA), originally with the purpose of achieving clinical remission and now extending to structural remission at the radiographic level." (PMID 22629396, 2012). "It was reported previously that Th1 cytokines like IL-1β, TNF-α were higher in PsA compared to rheumatoid arthritis (RA)." (PMID 22417743, 2012). "Glucose-6-phosphate isomerase (GPI)-induced arthritis is a closer model of human rheumatoid arthritis based on its association with CD4+ T cells and cytokines such as TNF-α and IL-6 than CIA." (PMID 23251456, 2012). "Specific examples include TNF-α inhibitors in rheumatoid arthritis and inflammatory bowel disease and statins in cardiovascular disease." (PMID 23056240, 2012). "B cell depletion therapy is efficacious in rheumatoid arthritis (RA) patients failing on tumor necrosis factor (TNF) blocking agents." (PMID 22540992, 2012). "In the past 2 decades, use of TNF-α antagonists have revolutionized the treatment of rheumatoid arthritis, inflammatory bowel disease, psoriasis, and other inflammatory conditions." (PMID 23092579, 2012). "TNF-α promotes granuloma formation, which is involved in preventing the dissemination of bacilli, and anti-TNF-α treatment for rheumatoid arthritis increases the risk of active tuberculosis development." (PMID 22719887, 2012). "The inhibitory effect on TNF-α and IL-6 production by magnolol may contribute to the bone antiresorbing effect of magnolol and possibly also play a role in the reduction of bone loss seen in the vicinity of inflammatory processes such as rheumatoid arthritis and periodontal disease." (PMID 22474400, 2012). "Similar findings have been reported in the treatment of the animal model of rheumatoid arthritis with TNF-α and TNFR1 neutralizing antibodies." (PMID 22666471, 2012). "TNFα is known to be secreted during early stages of acute and chronic inflammatory diseases such as rheumatoid arthritis, asthma, septic shock and other allergic diseases." (PMID 23136560, 2012). "Tumor necrosis factor alpha (TNFα) inhibitor therapy has greatly improved outcome in patients with moderate and severe rheumatoid arthritis (RA)." (PMID 22685579, 2012). "Tumor necrosis factor (TNF) is a major pro-inflammatory cytokine playing an important role in the pathogenesis of chronic inflammatory diseases such as rheumatoid arthritis, Crohn's disease or psoriatic arthritis." (PMID 22666310, 2012). "Interestingly, recent studies suggest that the therapeutic efficacy of anti-tumor necrosis factor-α therapies may result from the inhibition of CCL20 in rheumatoid arthritis synovium as this chemokine mediates key pathogenic events such as the recruitment of Th17 cells to the inflamed joints." (PMID 21961038, 2011). "Etanercept (Enbrel®), infliximab (Remicade®), and adalimumab (Humira®) are TNF inhibitors that are used in animal disease models of MS and have been approved for treatment of patients with rheumatoid arthritis, inflammatory bowel disease, and psoriasis." (PMID 22194778, 2011). "Infliximab, a chimeric monoclonal antibody to TNF-α, was developed and used to treat systemic inflammatory disorders such as rheumatoid arthritis and Crohn's disease." (PMID 21352523, 2011). "TNF-α has been demonstrated to be one of the main inflammatory mediators that involved in autoimmune diseases, such as rheumatoid arthritis, systemic sclerosis." (PMID 22069489, 2011).
rheumatoid arthritis (continued). "The existing TNF-α blocker treatments for rheumatoid arthritis are only effective for approximately 2/3 of the affected population." (PMID 21423713, 2011). "Present evidence has shown that antagonism of TNF-α by expression of sTNFR can ameliorate inflammatory diseases such as rheumatoid arthritis or reduce TNF-α mediated cytopathicity." (PMID 21569583, 2011). "TNF-alpha blockers represent one of the most important therapeutic strategies for rheumatoid arthritis, but their use has raised the question about their safety profile, particularly in respect to viral infections/reactivations." (PMID 22570799, 2011). "Pro-inflammatory CD16+ monocytes have increased potential to produce pro-inflammatory cytokines such as TNFα and are increased in inflammatory diseases, such as rheumatoid arthritis." (PMID 21492422, 2011). "The anti-TNF inhibitor, etanercept is administered as a once or twice weekly subcutaneous injection for the treatment of rheumatoid arthritis, psoriasis, ankylosing spondylitis, psoriatic arthritis and juvenile idiopathic arthritis (JIA)." (PMID 21672203, 2011). "Baseline characteristics of patients in remission following TNF inhibitor therapy and in patients with active rheumatoid arthritis." (PMID 22102879, 2011). "In this regard, TNF-α and HMGB1 have been intimately linked to the pathology of several inflammatory diseases, such as sepsis, rheumatoid arthritis and Crohn's disease." (PMID 21887276, 2011). "In humans, anti-TNF-alpha antibodies (e.g., Remicade® (infliximab)) are used to treatment several common inflammatory diseases, including rheumatoid arthritis, psoriatic arthritis and Crohn's disease." (PMID 21887218, 2011). "The mainstay of pharmacologic therapy for rheumatoid arthritis includes the use of disease-modifying agents like sulfasalazine and methothrexate, and more recently, anti-tumor necrosis factor-α agents." (PMID 21418592, 2011). "In fact, it has been demonstrated that TNF-alpha plays a role in various inflammatory diseases such as rheumatoid arthritis (RA), ankylosing spondylitis, psoriasis, Crohn's disease, psoriatic arthritis, and juvenile idiopathic arthritis." (PMID 22074550, 2011). "Only 21 to 33% of Rheumatoid Arthritis Observation of Biologic Therapy registrants would have been eligible for the trials, and this ineligible group demonstrated lower TNF inhibitor response rates than RCT enrolees who received biologic therapy." (PMID 21624184, 2011). "An earlier focus of our laboratory has been the study of the effects of tumour necrosis factor-α (TNF), whose expression is dysregulated in inflammatory diseases such as rheumatoid arthritis, on T cell function." (PMID 21915344, 2011). "Previous studies in rheumatoid arthritis (RA) also found that females were less likely to achieve remission on anti-TNF-α treatment." (PMID 21689401, 2011). "In the case of immune-based joint diseases like rheumatoid arthritis, high quantities of pro-inflammatory cytokines, such as TNF, are found in the synovial fluids and the amount of TNF elevation closely correlates with disease severity." (PMID 21658227, 2011). "In this series (1998 until 2002) there were 42 reported cases of histoplasmosis after the first anti-TNF treatments were approved for the treatment of rheumatoid arthritis in 1998." (PMID 21605439, 2011). "The objective of this study was to investigate the effects of tumor necrosis factor (TNF)-α inhibitors on circulating T helper-type 17 (Th17) cells and Th17-related cytokines in patients with rheumatoid arthritis (RA)." (PMID 21801431, 2011). "Anti tumor necrosis factor (TNF) agents are emerging in the frontline management of rheumatoid arthritis (RA) in the current era of biological treatment." (PMID 22383918, 2011). "It is therefore necessary to discover new molecular intervention points involved in TNF-α blocker treatment of rheumatoid arthritis patients." (PMID 21423713, 2011).